ENSG00000294542 (novel transcript)
Gene: Long non-coding RNA gene on chromosome 9 (94,681,649 to 94,696,268, forward strand). Ensembl gene ENSG00000294542.
Gene Ontology:
Biological process: SRP-dependent cotranslational protein targeting to membrane, signal sequence recognition
Cellular component: signal recognition particle, endoplasmic reticulum targeting